MAD2L1 (mitotic arrest deficient 2 like 1)
Diseases named in the same sentence as MAD2L1 in open-access papers (continued):
Sharing a sentence is not in itself a finding about the gene and the disease.
tumor (continued). "IHC revealed that LZU‐WZLYCS01 treatment markedly downregulated the expression of FGFR3, MAD2L1, and Ki‐67 in tumor tissues." (PMID 41168906, 2026). "To further investigate the potential mechanism by which MAD2L1 promotes tumor cell proliferation, we analyzed cell cycle distribution using flow cytometry." (PMID 40231267, 2025). "A study based on microarray data identified five genes (CDK1, CDC20, CCNB1, CENPF, and MAD2L1) related to the tumor stage, early diagnosis, and poor outcomes." (PMID 40282296, 2025). "We analyzed MAD2L1 expression in six surgically resected HB tumor tissues and adjacent normal liver tissues." (PMID 40231267, 2025). "In rescue experiments using MAD2L1‐silenced tumor cells, NaLa treatment showed minimal capacity to enhance proliferation." (PMID 40145796, 2025). "Our findings elucidate the mechanism of MAD2L1 signaling activation in tumor tissues under high‐sugar dietary conditions." (PMID 40145796, 2025). "The expression of MAD2L1 was studied in resected iCCA specimens and correlated with tumor size, pathological grade, clinical stage, and inversely with overall survival." (PMID 38909034, 2024). "Subsequent experiments showed that overexpression of MAD2L1 increased the proliferation of iCCA cell lines in vitro, and knockout of Mad2l1 markedly reduced the tumor burden and prolonged the survival of mice in vivo." (PMID 38909034, 2024). "Considering biopsies and resections together, there was a statistically significant difference of BAG2 and MAD2L1 expression levels in tumor tissues as compared to RMP." (PMID 39300217, 2024). "As a first step, we analyzed the TIMER2.0 and TCGA databases for MAD2L1 expression levels in all human tumor data." (PMID 36637946, 2023). "Overall, we found that NPM3 was positively associated with genes that promote tumor proliferation, with NPM3 positively regulating the expression of CCNA2 and MAD2L1, and NPM3 was negatively correlated with the tumor suppressor RASSF5." (PMID 37254219, 2023). "Subsequently, miR-139-5p was selected as the most potent MAD2L1 upstream tumor-suppressive miRNA based on tumor grade expression and survival analyses." (PMID 36637946, 2023). "By comparing and analyzing the significantly down-regulated genes in dormant tumor cells with MYC_TARGETS_V1, MYC_TARGETS_V2, three significantly down-regulated genes were obtained: Ccna2, Mad2L1 and Plk1." (PMID 35305591, 2022). "It has been shown that interrupting the function of MAD2L1 in mammalian cells can affect the process of spindle examination and lead to the development of aneuploid cells or tumours." (PMID 35037540, 2022). "The abnormal expression of MAD2L1 is related to the progression of most tumors and the process of chemotherapy resistance; many types of human tumor cell chromosomal defects are related to the abnormal expression of MAD2L1." (PMID 35305591, 2022). "Abnormal expression of MAD2L1 induces chromosome instability and aneuploidy in cells to promote tumor formation." (PMID 35456460, 2022). "This study uses the GEO database and USCS Xena database to reveal for the first time that the MYC targeting gene MAD2L1 is potentially related to tumor dormancy mechanisms." (PMID 35305591, 2022). "Studies have shown that reducing the expression of MAD2L1 can inhibit tumor cell migration and invasion, thereby hindering tumor occurrence and development." (PMID 34696748, 2021). "By using TCGA and THPA databases, we found five genes, CDK1, CDC20, CCNB1, CENPF, and MAD2L1, that were related to the early diagnosis, tumour stage, and poor outcomes of HBV-HCC." (PMID 34603487, 2021). "Our bioinformatics analysis showed that MAD2L1 was highly expressed in tumor tissues compared with normal tissues." (PMID 34126961, 2021). "Among the five hub genes, the altered CCNA2, DLGAP5, MAD2L1 and KIF2C were associated with tumor grade, and were significantly up-regulated in LUSC compared with other NSCLC, implicating crucial roles of them in LUSC progression." (PMID 32411535, 2020).
tumor (continued). "The expression of MAD2L1 was higher in tumor cells than in normal cells, which is similar to the results from the four datasets in GEO and the GEPIA results, suggesting that our results for these genes are reliable." (PMID 32153633, 2020). "Our data highlighted that MAD2L1 gene has shown different genetic aberrations in CRC whereby overexpression, missense mutations (in the 31% of tumours) and alternative splicing." (PMID 31949199, 2020). "Among the five hub genes with prognostic values genes, four (CCNA2, DLGAP5, MAD2L1 and KIF2C) were associated with LUSC tumor grade." (PMID 32411535, 2020). "In all but one T-ALL tumor from Lck-Cre::Mad2l1f/f::Trp53f/f animals (tumor 33, in which switching was incomplete and protein present) Mad2l1 DNA, mRNA, and protein were below the level of detection." (PMID 28318489, 2017). "CDK1 and MAD2L1 were selected for further study due to their known role in regulating tumor cell cycle and mitosis." (PMID 27835911, 2016). "Our findings revealed that MAD2L1 expression was significantly upregulated in tumor tissues." (PMID 39387242, 2024). "As most iCCA samples are TBX3 low and MAD2L1 high, it is tempting to hypothesize that these tumors might be less responsive to the chemotherapy due to the more aggressive tumor cell phenotypes." (PMID 38909034, 2024). "This was followed by an analysis of MAD2L1 immune scores expressed in tumor and normal tissues." (PMID 36637946, 2023). "Protein-protein interaction (PPI) analysis revealed that cyclin B1 (CCNB1), mitotic arrest deficient 2 like 1 (MAD2L1), H2A family member Z (H2AFZ) and CXCL2 may be the important protein molecules involved in CXCL3-related tumor biology." (PMID 38031087, 2023). "Based on downstream analysis, 5 hub genes, including CDK1, CDC20, CCNB1, CENPF, and MAD2L1, that could play a critical role in the early diagnosis, tumour stage, and poor outcomes of HBV-HCC were identified." (PMID 34603487, 2021). "Consequently, MAD2L1 is also an important indicator of the early diagnosis, tumour stage, and poor outcomes of HCC." (PMID 34603487, 2021). "CCNA2, DLGAP5, MAD2L1, and KIF2C were significantly up-regulated compared to other subtypes, and associated with tumor stage in LUSC, suggesting that they might tightly be involved in progression and prognosis of LUSC." (PMID 32411535, 2020). "Lowering the expression of MAD2L1 by siRNAs could reduce tumor cell growth and inhibit cell migration and invasion." (PMID 29467930, 2018). "The differences between single-cell and population-level measures of aneuploidy are most parsimoniously explained by postulating that Mad2l1-null tumors experience ongoing CIN but that specific aneuploid genomes predominate in a tumor as a result of tissue-specific selection." (PMID 28318489, 2017). "Our findings suggest that this could be linked to the activation of downstream cell cycle gene expression by MAD2L1, which enhances cell proliferation and bypasses mitotic checkpoint abnormalities, thereby helping HB cells maintain stability and promoting tumor growth." (PMID 40231267, 2025). "Moreover, our results suggest that MAD2L1 may exert oncogenic effects by increasing tumor immune cell infiltration and checkpoint expression." (PMID 36637946, 2023). "LZU‐WZLYCS01 intracellularly releases A2, which targets MAD2L1 to activate the cGAS‐STING pathway and induce tumor cell apoptosis." (PMID 41168906, 2026). "In contrast, the Akt/NICD/sgEGFP group exhibited many tumor nodules, thereby confirming that knockout of Mad2l1 can suppress iCCA growth and development in the Akt/NICD tumor model." (PMID 38909034, 2024). "Our findings demonstrate that ncRNA-mediated upregulation of MAD2L1 in HCC is closely related to poor prognosis and tumor infiltration." (PMID 36637946, 2023).
tumor (continued). "And our results showed that the expression levels of MAD2L1 and CCNB2 correlated with the overall survival of patients with RMS and the clinical stage of the tumor." (PMID 34838000, 2021). "MAD2L1, NCAPG, PBK, and PLK4) was validated using qRT-PCR in MDA-MB-231 and BT-549.Taken together, our data highlighted activation of several tumor suppressor transcriptional regulatory networks in response to DNMT inhibition leading to tumor cell death." (PMID 34565361, 2021). "Gene set enrichment analysis (GSEA) revealed that the genes in MAD2L1 and CCNB2 groups with high expression were mainly related to the mechanism of tumour metastasis and recurrence." (PMID 34838000, 2021). "To further verify the results of bioinformatics analysis, we applied qRT-PCR to validate the mRNA levels of HMMR, SPP1, FN1, CCNB1, CXCL8, MAD2L1 and CCNA2 in 10 paired tumor and adjacent normal tissues with qRT-PCR." (PMID 34126961, 2021). "Further clinical validation of the tumor promoter and worse prognosis predictor function of NDC80 and MAD2L1 in local LUAD and LUSC patients as well as the genes’ relation with BUB1B and AURKA is on our way." (PMID 32795325, 2020). "Consistent with the expression results analyzed by ONCOMINE, the expression levels of CDK1, CCNB1, CCNB2, MAD2L1, and TOP2A assessed by TCGA data were all upregulated in tumor tissues compared with the normal controls (all P < 0.05)." (PMID 31886163, 2019). "By interacting with MAD2L1, HDAC1, and histone deacetylase 276,77, this protein likely plays a role in cell cycle control and tumor suppression." (PMID 30531795, 2018). "Both MAD2L1 and BUB1 expression were found to be higher in tumor than in adjacent non-tumor tissues (5.97±0.66 versus 5.36±0.38 for MAD2L1, 6.80±1.14 versus 5.50±0.74 for BUB1, respectively, and both P<0.0001) in this database." (PMID 26287798, 2015). "Surprisingly, that study also showed that let-7 represses several tumour suppressor genes (BRCA1, BRCA2, FANCD2, and PLAGL1, among others) and checkpoint regulators (CHEK1, BUB1, BUB1B, MAD2L1, and CDC23, among others)." (PMID 20179807, 2010). "The Tumor IMmune Estimation Resource (TIMER) database was used as a next step to investigate the relationship between immune cell infiltration and immune checkpoints in HCC using MAD2L1 expression as a marker." (PMID 36637946, 2023). "The expression levels of MAD2L1 and CCNB2 are potential indicators of TME status changes in RMS, which may help guide the prognosis of patients with RMS and the clinical staging of tumours." (PMID 34838000, 2021). "One of our best results is the recurrent deregulation of MAD2L1 gene in CRC, in concordance with the high frequency of CIN in these tumours: we think that could be used it as a new potential prognostic biomarker." (PMID 31949199, 2020). "The results indicated that the high MAD2L1 expression predicted shorter survival times compared with the low MAD2L1 expression in HCC patients with tumor stage 1 (log-rank P = 0.0072), tumor stage 2 (log-rank P = 0.022), and tumor stage 3 (log-rank P = 0.0015)." (PMID 31886163, 2019). "Collectively, these findings suggest that MAD2L1 and CDC20 may be key regulators of tumor severity, ultimately dictating patient survival." (PMID 30245591, 2018). "To establish that the Mad2l1 locus was in fact lost in tumor cells and that no RNA or protein was expressed, we analyzed DNA structure by genomic PCR and aCGH, mRNA levels using qPCR, and protein levels by Western blotting of tumor samples." (PMID 28318489, 2017).
tumor (continued). "Overexpression of MAD2L1 and PTTG1 (securin) has been observed in several tumor types." (PMID 25978455, 2015). "In contrast, MAD2L1 was strongly expressed in the nucleus and cytoplasm of most iCCA samples (68/82, 82.3%), while no MAD2L1 immunolabeling could be observed in the remaining 14 tumor specimens." (PMID 38909034, 2024). "Moreover, overexpression of CDK1, CCNB1, CDC20, BUB1, MAD2L1, and BUB1B in tumour tissues could increase cell proliferation and division." (PMID 33035258, 2020). "To validate the expression of ASMP, BUB1, CENPF, MAD2L1, NCAPG, SGO2, and TOP2A genes in tumor samples and adjoining nontumor samples, we measured their relative mRNA expressions using qPCR." (PMID 36072975, 2022). "In addition, we found from publicly available data that expression of MAD2L1 and BUB1 was higher in tumor than in adjacent non-tumor tissues." (PMID 26287798, 2015).
infection (2 papers, 2010 to 2024). The state of being infected such as from the introduction of a foreign agent such as serum, vaccine, antigenic substance or organism. "NN1172-infection leads to the down-regulation of many genes related to cell cycle and DNA replication genes, including MCM 2 ~ 6, CDK1 ~ 2, CCNB2, ANAPC2, MAD2L1, WEE1, RBL1, RB1." (PMID 38362295, 2024). "Furthermore, seven genes (CDK1, TYMS, MCM5, KIF11, CCNB2, MAD2L1, and MCM4) have been identified as core hub genes involved in cell-cycle regulation, potentially serving as mediators in the pathogenesis triggered by NN1172 infection within the thymus." (PMID 38362295, 2024).
colon (1 paper, 2021). "Interestingly, the downregulated DEGs, such as MAD2L1, CCNA2, MCM2, MCM4, FEN1, and CDK6, were enriched in DNA replication, tyrosine metabolism, and cell cycle pathways, which are commonly upregulated in colon cancer." (PMID 34521988, 2021).
kidney disease (1 paper, 2025). "To validate the potential genes is functionally in kidney disease, we choose whole genes (CDC16, CDC20, CDC27, MAD2L1, ANAPC1, ANAPC7, BUB1B) from first highest score subnetwork obtained from Cytoscape MCODE plugin from upregulated genes PPI as hub genes." (PMID 40034749, 2025).
MAD2L1 also shares sentences with these, for which no sentence is quoted: cholangiocarcinoma (4 papers); neuroblastoma (3); adenocarcinoma (2); glioblastoma (2); non-small cell lung carcinoma (2); rectal cancer (2); adult T-cell leukemia (1); bladder urothelial carcinoma (1); chronic hepatitis C (1); Cirrhosis (1); colon adenocarcinoma (1); colorectal tumors (1); germ cell cancer (1); head and neck squamous cell carcinoma (1); large cell lung cancer (1); lung squamous cell carcinoma (1); lymphoma (1); malignant pleural mesothelioma (1); medulloblastoma (1); multiple myeloma (1); myotonic dystrophy (1); neuroendocrine tumor (1); Obesity (1); oral cancer (1); ovarian carcinoma (1); ovarian serous adenocarcinoma (1); prostate adenocarcinoma (1); psoriasis (1); stomach adenocarcinoma (1); triple-negative breast carcinoma (1).
A further 2 diseases each share a sentence with MAD2L1 in 1 paper.